MAGEA3 (MAGE family member A3)
Description:
Activator of ubiquitin ligase activity of RING-type zinc finger-containing E3 ubiquitin-protein ligases that acts as a repressor of autophagy. Proposed to act through recruitment and/or stabilization of the Ubl-conjugating enzyme (E2) at the E3:substrate complex. May play a role in embryonal development and tumor transformation or aspects of tumor progression. In vitro promotes cell viability in melanoma cell lines. Antigen recognized on a melanoma by autologous cytolytic T-lymphocytes.
Synonyms: CT1.3; MAGE3; HYPD; HIP8; MGC14613
Tractability: Small molecule: a structure with a bound ligand is known. PROTAC: UniProt records ubiquitination sites on it; ubiquitination databases record sites on it. Other modalities: a drug acting on it is in phase 2 or 3 trials.
Gene: Protein-coding gene on chromosome X (152,698,767 to 152,702,347, forward strand). Ensembl gene ENSG00000221867.
Gene Ontology:
Molecular function: caspase binding; protein binding; histone deacetylase binding
Biological process: negative regulation of autophagy; negative regulation of endoplasmic reticulum stress-induced intrinsic apoptotic signaling pathway; negative regulation of protein processing; negative regulation of transcription by RNA polymerase II
Cellular component: endoplasmic reticulum; nucleus
Homologues: Orthologues: zebrafish ndnl2 (20% identical), Drosophila melanogaster MAGE (16% identical). Paralogues in human: MAGEA6 (96% identical), MAGEA12 (85% identical), MAGEA2 (84% identical), MAGEA2B (84% identical), MAGEA4 (68% identical), MAGEA1 (67% identical), MAGEA8 (63% identical), MAGEA11 (60% identical), MAGEA9 (60% identical), MAGEA9B (60% identical), MAGEA10 (51% identical), MAGEB16 (41% identical), and 25 more.
Diseases named in the same sentence as MAGEA3 in open-access papers:
MAGEA3 is named in the same sentence as 111 diseases in open-access papers, as found by Europe PMC text mining. Sharing a sentence is not in itself a finding about the gene and the disease. The quoted sentences say what the papers report.
melanoma (239 papers, 1996 to 2025). A malignant, usually aggressive tumor composed of atypical, neoplastic melanocytes. "In the most notable example, MAGEA3-specific engineered T-cells were associated with severe off-target toxicity in melanoma patients." (PMID 37377956, 2023). "MAGEA3 is a well-known melanoma-associated antigen that binds to HLA-A*01:01." (PMID 30832312, 2019). "Studies have reported that MAGEA3 can promote proliferation or inhibit apoptosis of various cell lines of melanoma, CRC, gastric cancer, and cervical cancer." (PMID 40342736, 2025). "The initial identification of MAGEA3 as a tumor neoantigen in melanoma and non-small cell lung cancer (NSCLC) has prompted many MAGEA3-based cancer vaccines and adoptive T cell therapy studies." (PMID 40342736, 2025). "Recently, a phase-III trial assessing MAGEA3 immunotherapy in stage III melanoma patients in the adjuvant setting failed." (PMID 35964339, 2022). "Recently, promising clinical response was observed in melanoma patients who failed anti-PD1 treatment by using the of RNA-lipoplex vaccine (targeting four tumor associated antigens (TAA) namely NY-ESO-1, MAGEA3, tyrosinase and TPTE; FixVac)." (PMID 33937323, 2021). "In contrast, the top SFPQ-enriched mRNA transcripts in melanoma cells were generally associated with disease progression, such as AMIGO2, MAGEA3, MAGEA1, and the transcription factor, SOX10." (PMID 34218270, 2021). "MAGE-A proteins, including three of the four genes identified in our analysis (MAGEA2, MAGEA3, and MAGEA6), have recently been implicated in resistance to CTLA-4 ICB in melanoma patients." (PMID 32117236, 2020). "In healthy individuals (and not in melanoma patients), melanoma-specific T lymphocytes displaying a strong reactivity against peptides of melanoma antigens Tyrosinase–MAGEA3–Melan-A/Mart-1–Pmel 17gp100 and NY-ESO-1 have been identified." (PMID 32028565, 2020). "Gene expression analysis of five melanoma-associated genes, including MLANA, TYR, MAGEA3, ABCB5 and PAX3, showed that at least one transcript was detected in 18 out of 43 samples analysed (42%)." (PMID 32037400, 2020). "Several of the CTAg genes detected in the CoMMpass analysis (MAGEA3, A6, A12, and CSAG1) were also in the CTAg gene set associated with resistance to anti-CTLA-4 therapy in melanoma." (PMID 32133047, 2020). "In contrast, clinical trials of MAGEA3 have been more successful in melanoma, consistent with our observed positive correlation between MAGEA3 expression and CD8 T-cell abundance." (PMID 27549193, 2016). "Simultaneously, others identified similar signatures to be predictive of responsiveness in patients with melanoma vaccinated with four TAs plus IL-12, dendritic cells loaded with multiple TAs, or melanoma and lung cancer patients receiving a MAGEA3 peptide vaccine." (PMID 22576055, 2012). "However, the two largest phase III clinical trials targeting MAGEA3 immunotherapeutic as an adjuvant therapy for stage III melanoma and nonsmall cell lung cancer failed, which is stagnating the progress of immunotherapeutic, and research on MAGEA3 also have declined." (PMID 34970496, 2021). "We continued to assess the effect of DAC treatment on the expression of MAGEA1, MAGEA3/MAGEA6, and MAGEA9 in a broad panel consisting of 37 cell lines originating from female reproductive organ tumors, melanoma, hematopoietic, or other cancers." (PMID 40791813, 2025). "Several ongoing clinical trials for cancer treatment, including those targeting melanoma and neuroblastoma, utilize MAGEA1 or MAGEA3 as targets." (PMID 41345672, 2025). "In a notorious example, engineered T-cells specific to MAGEA3 (EVDPIGHLY) also recognized a TITIN-derived peptide (ESDPIVAQY) expressed by cardiac cells, inducing lethal damage in melanoma patients." (PMID 37377956, 2023). "In this study, the uMAGEA assay increased melanoma detection by 13% compared with the MAGEA1 assay alone, and by 17% compared with the MAGEA3 assay alone in melanoma tumors." (PMID 35205608, 2022).
melanoma (continued). "A recent study in melanoma suggests that this may be possible: RNA-LPX vaccine encoding MAGEA3, NY-ESO-1, tyrosinase and transmembrane phosphatase with tensin homology (TPTE) were tested in checkpoint-inhibitor (CPI)-treated patients with unresectable melanoma." (PMID 32942747, 2020). "Transcripts of MLANA, TYR, MAGEA3, PAX3, and ABCB5 were successfully identified from a single melanoma cell, as reflected by the increase in reciprocal Ct values (1/Ct)." (PMID 28978038, 2017). "Similarly, it was shown that MAGEA3 suppresses apoptosis of multiple myeloma cells, and MAGE-C suppresses apoptosis of melanoma and colon cancer cell lines." (PMID 34788311, 2021). "For example, MAGEA1 is upregulated in lung cancer, melanoma, and gastric cancer; MAGEA3 is upregulated in breast and lung cancer; MAGEA4 is upregulated in melanoma; MAGEA5 is upregulated in head and neck cancer; and MAGEA9 is upregulated in liver and colon cancer." (PMID 34202157, 2021). "Analysis of cancer/testis antigen expression and CD8 T-cell abundance suggests that MAGEA3 is a potential immune target in melanoma, but not in non-small cell lung cancer, and implicates SPAG5 as an alternative cancer vaccine target in multiple cancers." (PMID 27549193, 2016). "The present study focused on the anti-tumor effect against TC1-MAGE-A3 tumors, but tumor protection was also obtained against other MAGEA3 -transfected murine cell lines (B16-MAGE-A3 melanoma or CT26-MAGE-A3 colon carcinoma) (data not shown)." (PMID 24830315, 2014). "Additionally, BNT111, a liposomal RNA vaccine, targets four non-mutated tumor-associated antigens, including New York esophageal squamous cell carcinoma 1 (NY-ESO-1), tyrosinase, MAGE family member A3 (MAGE-A3), and transmembrane phosphatase with tensin homology (TPTE), in melanoma." (PMID 39789208, 2025). "However, expression of TDRD9 is not correlated with that of MAGEA1, MAGEA2, MAGEA3, or MAGEA4, which are CTA genes often expressed in lung cancer and melanomas." (PMID 29515758, 2018).
lung cancer (41 papers, 2007 to 2025). A malignant neoplasm involving the lung. "The immunotherapy related to MAGEA3 in lung cancer has entered the clinical trial stage, and the immunogenicity and safety are good." (PMID 38555374, 2024). "For example, MAGEA3 and MAGEA6 are both associated with colorectal and lung cancers, and MAGEA6 and MAGEA11 are coexpressed in prostate cancer." (PMID 34202157, 2021). "In particular, MAGEA3 and MAGEA6 expression are highly correlated in colon and lung cancer, as is MAGEA6 and MAGEA11 expression in prostate cancer." (PMID 34202157, 2021). "One possible interpretation of these results is that the host immune system in lung cancer patients fails to recognize MAGEA3 as a neoantigen, which might explain the ineffectiveness of MAGEA3-based vaccines in lung cancer." (PMID 27549193, 2016).
myeloma (31 papers, 2011 to 2024). "An antigen-specific cancer immunotherapeutic combining recombinant MAGEA3 and an adjuvant has been developed and is in phase I testing as post transplant consolidation in patients with multiple myeloma." (PMID 22100031, 2011). "MAGEA3 has previously been described to prevent apoptosis through the upregulation of BIRC5 (Survivin), a member of the inhibitor of apoptosis family, in multiple myeloma." (PMID 34166362, 2021). "This analysis revealed significant down-regulation by CYCLON knockdown of a proliferation gene expression signature that includes cancer testis antigens (e.g. MAGEA1, MAGEA3, MAGEA6, GAGE1), and that characterizes an aggressive subtype of multiple myeloma." (PMID 23828858, 2013). "The pathologic plasma cells of multiple myeloma commonly express two specific CT antigens, CT7 and MAGEA3 as demonstrated by immunohistochemistry and RT-PCR and expression is increased with advanced disease and higher degree of plasma cell proliferation." (PMID 22100031, 2011). "Moreover, in multiple myeloma, MAGEA3 knockdown increases the levels of the proapoptotic proteins BAX and BIM and the cyclin-dependent kinase (CDK) inhibitor p21; this suggests that MAGEA3 represses apoptosis by regulating BAX, BIM, and p21, and induces cell proliferation." (PMID 34202157, 2021).
non-small cell lung carcinoma (31 papers, 2011 to 2025). A group of at least three distinct histological types of lung cancer, including non-small cell squamous cell carcinoma, adenocarcinoma, and large cell carcinoma. "The second trial evaluates oncolytic MG1-MAGEA3 with Ad-MAGEA3 in combination with pembrolizumab (anti-PD-1 antibody) for previously treated metastatic non-small cell lung cancer." (PMID 39066256, 2024). "The second is evaluating the oncolytic MG1-MAGEA3 with Ad-MAGEA3 vaccine in combination with pembrolizumab (anti-PD-1 antibody) for patients with previously treated metastatic non-small cell lung cancer (NCT02879760)." (PMID 32455560, 2020). "Moreover, a family member, MAGEA3, is currently the target of a phase three clinical trial for non-small cell lung cancer." (PMID 25631659, 2015).
ovarian carcinoma (23 papers, 2010 to 2025). A malignant neoplasm originating from the surface ovarian epithelium. "MAGEA8 is a CT antigen whose expression in normal adult tissues is restricted to the testis and placenta; family members MAGEA3, MAGEA1 were also scored by immunotherapy experts (ranks 8 and 44 out of 75) and have been shown to be expressed in ovarian cancers." (PMID 26622942, 2015). "In particular, MAGEA3,6,11,12 as well as GAGE2,4,5,6 and 7 were found elevated in ovarian cancer cells resistant to paclitaxel and doxorubicin." (PMID 22141344, 2011).
breast carcinoma (18 papers, 2001 to 2024). "MAGEA3 expression levels were closely associated with markers of active histone modifications in breast cancer cell." (PMID 38555374, 2024). "MAGEA12 is reported to promote the expression of MAGEA2 and MAGEA3; The higher expression of MAGEA3 is reported to be accompanied by up-regulated expression and activity of ERα, which further leads tamoxifen resistance in breast cancer." (PMID 37857018, 2023). "MAGEA12 and MAGEA3 were the predominant isoforms that were expressed by breast cancer cells; their expression levels were also high compared with those of other genes belonging to the MAGE-A family." (PMID 34202157, 2021). "Consistent with this, we found that MAGEA12 and MAGEA3 expression was strongly correlated in breast cancer." (PMID 34202157, 2021). "The combination of β-HCG and tumor antigen MAGE family member A3 (MAGE-A3) expression in circulating breast cancer cells positively correlated with tumor size." (PMID 28754015, 2017). "In this form of breast cancer MAGEA3, for example, is expressed at 15-26% as compared with around 6% in unselected breast cancers." (PMID 25593980, 2014). "Therefore, we propose that monitoring the expression of both MAGEA12 and MAGEA3 may help predict the prognosis and malignancy of breast cancer better than the expression of other members of the MAGE-A family genes." (PMID 34202157, 2021). "Thus, our data suggest that the aberrant expression of MAGEA12 and MAGEA3 genes may be useful for classifying and predicting malignant breast cancer phenotypes." (PMID 34202157, 2021). "In breast cancer, it is verified that overexpression of MAGEA2 and MAGEA3 enhanced the activity of ERα, by which it leads to tamoxifen resistance." (PMID 37857018, 2023). "Significantly, we also observed that breast cancer patients with high MAGEA12 and MAGEA3 expression had a poor prognosis." (PMID 34202157, 2021). "The RNA-seq data also indicated that the most highly expressed MAGE-A isoform in breast cancer cell lines was MAGEA12, followed by MAGEA3." (PMID 34202157, 2021). "We also conducted an overall survival analysis of 986 breast cancer patients in the TCGA database whose MAGEA12 and MAGEA3 expression in their tumors had been measured." (PMID 34202157, 2021). "In this study, we analyzed the RNA-sequencing (RNA-seq) data of 70 breast cancer cell lines and found that MAGEA12 and MAGEA3 were highly expressed in a subset of these lines." (PMID 34202157, 2021). "However, a subset of breast cancer cell lines, including MDAMB468 and SKBR3, expressed both MAGEA12 and MAGEA3." (PMID 34202157, 2021). "Overall, 19 breast cancer cell lines expressed MAGEA12, and 13 of these also expressed MAGEA3." (PMID 34202157, 2021). "MAGEA2, MAGEA3, MAGEA4, MAGEA6, and MAGEA12 are up-regulated in the CDKN2A alteration group, amongst which MAGEA3 (HR=1.61[1.27-2.04], p=8.2e-5), MAGEA4 (HR=1.38[1.08-1.77], p=0.011), and MAGEA12 (HR=1.65[1.10-2.48], p=0.015) are accompanied by worse prognosis in breast cancer." (PMID 37857018, 2023). "In summary, prior literature suggested breast cancer as a relatively “CT-poor” tumor type, and CT antigen-based therapeutic cancer vaccine trials, e.g. MAGEA3 and NY-ESO-1 trials, have not been actively pursued in breast cancer for this reason." (PMID 21437249, 2011).
metastatic melanoma (16 papers, 2010 to 2024). A melanoma that has spread from its primary site to another anatomic site. "In situ xenografts of human thyroid cancer cells overexpressing MAGEA3 increased the ability of tumor growth and metastasis to the lung, while MAGEC knockdown delayed the formation of metastatic melanoma in vivo." (PMID 34737950, 2021).
bladder cancer (14 papers, 2005 to 2025). "A data analysis of bladder cancer patients further uncovers the possibilities of utilizing MAGEA2, MAGEA3, MAGEA4, MAGEA6, MAGEA10, MAGEA11, and MAGEA12 members as diagnostic biomarkers for bladder cancer." (PMID 38254738, 2024). "This included strong upregulation of cancer‐testis antigens (MAGEA3, MAGEA6, MAGEA10) and neuroendocrine‐associated genes such as NEB and NELL2, features linked to higher tumour grade, invasion and lineage plasticity in bladder cancer." (PMID 41425537, 2025). "Next, we determined the predicted location and protein–protein interaction of MAGEA3 and MAGEA6 genes in bladder cancer." (PMID 38254738, 2024). "It was found that frequencies of genomic alterations among MAGEA family members in bladder cancer were MAGEA1 1.8%, MAGEA2 1.6%, MAGEA3 1.9%, MAGEA4 1.6%, MAGEA6 2.6%, MAGEA8 1.7%, MAGEA10 2%, MAGEA11, 2.1%, and MAGEA12 2.4%." (PMID 38254738, 2024). "To further understand the association between MAGEA3 and MAGEA6 with S100A9, we explored the OncoDB cancer database, a large-scale multi-omics database, and performed pairwise gene expression correlation analysis between MAGEA3 and MAGEA6 and S100A9 in bladder cancer patients." (PMID 38254738, 2024). "Due to their highly antigenic properties and other diverse roles during cancer progression, the aberrant expression of MAGEA family, especially MAGEA3 and MAGEA6, may serve as prognostic biomarkers for poor outcomes in bladder cancer patients." (PMID 38254738, 2024). "Interestingly, MAGEA2, MAGEA3, MAGEA4, MAGEA6, MAGEA10, MAGEA11, and MAGEA12 exhibited significant differences in their expression in bladder cancer compared to normal bladder samples." (PMID 38254738, 2024). "These values suggest that MAGEA3 and MAGEA6 may serve as prognostic biomarkers for bladder cancer patients." (PMID 38254738, 2024).
gastric cancer (13 papers, 2013 to 2025). A primary or metastatic malignant neoplasm involving the stomach. "Simultaneously, high MAGEA3 expression was linked to the lymph node metastasis of gastric cancer, which was verified in subsequent serological studies." (PMID 34970496, 2021). "MAGEA3 may be used not only as a diagnostic agent for gastric cancer patients but also as a potential target antigen for gastric cancer immunotherapy." (PMID 34970496, 2021). "We believe MAGEA3 can serve as a new biomarker in gastric cancer and provide more effective therapies in the era of immunotherapy." (PMID 34970496, 2021). "Our findings provide novel insights into the role of MAGEA3 in GC, thereby highlighting the underlying mechanism of MAGEA3 influencing immune cell interaction with tumors and providing preliminary preparations for the detection and immunotherapy of MAGEA3 in gastric cancer." (PMID 34970496, 2021). "These all suggest that MAGEA3 plays an immunomodulatory role in gastric cancer." (PMID 34970496, 2021). "Moreover, hsa-miR-767-3p exhibited the strongest correlation with MAGEA3 (R = 0.795, p = 2.09e−82), and the expression of hsa-miR-767-3p was significantly different in gastric cancer and normal tissues." (PMID 34970496, 2021). "In this research, we analyzed the relationship between MAGEA3 and gastric cancer patients’ prognosis through the Cancer Genome Atlas (TCGA) database and investigated the effect of MAGEA3 expression on immune cell infiltration, further screening out MAGEA3-related proteins and interacting miRNA." (PMID 34970496, 2021). "We further use purified MAGEA3 protein for the detection of specific antibodies in the serum of GC patients to prove that MAGEA3 is related to the progression of gastric cancer." (PMID 34970496, 2021). "We also found the expression of MAGEA3 correlates with TMB, so we assume that the expression of MAGEA3 affects the immune status in gastric cancer." (PMID 34970496, 2021).